SNORD83 (Small nucleolar RNA SNORD83 )
Synonyms: LOC124903098
Gene: Small nucleolar RNA gene on chromosome 12 (64,575,665 to 64,575,741, forward strand). Ensembl gene ENSG00000223294.
Gene Ontology:
Biological process: RNA processing
Cellular component: nucleolus
Homologues: Orthologues: chimpanzee SNORD83 (99% identical), dog SNORD83 (77% identical), pig SNORD83 (77% identical), rabbit SNORD83 (74% identical), mouse Gm25128 (73% identical), rat Snord83 (70% identical), guinea pig SNORD83 (66% identical), zebrafish SNORD83 (64% identical), tropical clawed frog SNORD83 (62% identical), zebrafish SNORD83 (62% identical). Paralogues in human: SNORD117 (77% identical), SNORD84 (64% identical).